SUMF1 (sulfatase modifying factor 1)
Diseases named in the same sentence as SUMF1 in open-access papers (continued):
Sharing a sentence is not in itself a finding about the gene and the disease.
glioma (continued). "Furthermore, SUMF1 overexpression was significantly associated with adverse prognosis, IDH status, age, and histological subtypes in patients with glioma." (PMID 38460946, 2024). "The relationship between SUMF1 expression and the prognosis of glioma patients was explored." (PMID 38460946, 2024). "We found that inhibiting SUMF1 expression could deter the growth, migration, and invasion of glioma cells." (PMID 38460946, 2024). "Inhibiting the expression of SUMF1 could deter the proliferation, migration, and invasion of glioma cells through epithelial mesenchymal transition." (PMID 38460946, 2024). "Correlation between the overexpression of SUMF1 and adverse features in patients with glioma." (PMID 38460946, 2024). "The results of the wound healing and transwell tests showed that inhibiting SUMF1 expression could inhibit the U251 and U118 cell migration and invasion in glioma." (PMID 38460946, 2024). "The present comprehensive analysis and cellular experiments confirm that SUMF1 is overexpressed in glioma and may thus play a significant role in their progression." (PMID 38460946, 2024). "Preliminary evidence suggests that SUMF1 can affect the glioma progression through EMT." (PMID 38460946, 2024). "A risk model could predict poor prognosis and assess the relationship between the progression and prognosis of glioma based on the co-expression of long non-coding RNAs and SUMF1." (PMID 38460946, 2024). "A correlation between SUMF1 and glioma immune cell markers in the TCGA and GEPIA databases." (PMID 38460946, 2024). "This investigation further explores the roles that SUMF1 plays in glioma progression, as well as the mechanisms underpinning its actions, by using gene ontology (GO) analysis, cell counting kit-8 (CCK-8), wound healing, western blotting, and Transwell experiments." (PMID 38460946, 2024). "Inhibiting SUMF1 expression could deter the growth, migration, and invasion of glioma cells." (PMID 38460946, 2024). "We further confirmed the abnormal expression of FDX1, SUMF1, and SLC31A1 proteins in glioma samples by immunohistochemistry, and the correlation between high expression of FDX1 protein and poor prognosis in glioma patients." (PMID 36856182, 2023). "Since the HR values of FDX1, SUMF1, SLC31A1 were the highest in the seven‐gene signature, we were going to validate their protein expression in human glioma specimens." (PMID 36856182, 2023). "Similarly, in GBM, NDUFA6-DT demonstrates a negative correlation with SUMF1, CD109, MUC11, and MYBPH, which are all implicated in promoting glioma progression." (PMID 38674418, 2024). "For glioma with the IDH mutation, 1p/19q codeletion (codel or non-codel), gender (female or male), age (>60 or ≤60), and type of glioma (astrocytoma or oligodendroglioma), a significant correlation was observed between the overexpression of SUMF1 and adverse survival outcomes in patients." (PMID 38460946, 2024). "Likewise, glioma tissues with the IDH wild-type, 1p/19q codeletion (non-codel), and those collected from individuals aged >60 years exhibited an overexpression of SUMF1." (PMID 38460946, 2024).
COVID-19 (2 papers, 2023 to 2024). A disease caused by infection with severe acute respiratory syndrome coronavirus 2. "Recently, SUMF1 was associated with the outcomes of SARS-CoV-2 infection with the rs794185 polymorphism in the SUMF1 gene being associated with the severity of COVID-19." (PMID 38540990, 2024). "Here, we aimed to assess the possible association between SUMF1 gene polymorphism (rs794185) and the severity of COVID-19." (PMID 37344788, 2023). "In conclusion, our study for the first time identified that rs794185 in SUMF1 gene was associated with the severity of COVID-19." (PMID 37344788, 2023). "Subjects carrying the rs794185 locus C allele of the SUMF1 gene had a lower risk of severe COVID-19." (PMID 37344788, 2023). "In summary, our study for the first time identified that rs794185 in SUMF1 gene was associated with the severity of COVID-19." (PMID 37344788, 2023). "The risk of severe COVID-19 at the rs794185 site of the SUMF1 gene was significantly reduced using TT genotype as a reference." (PMID 37344788, 2023). "But in our study, we found a significant association between rs794185 in SUMF1 gene and COVID-19 severity (P = 0.0073)." (PMID 37344788, 2023). "The risk of severe COVID-19 at the rs794185 site of the SUMF1 gene was also significantly reduced in European population (GenOMICC: OR for C allele = 0.94, 95% CI = 0.90–0.98, P = 0.0037)." (PMID 37344788, 2023). "The risk of severe COVID-19 at the rs794185 site of the SUMF1 gene was significantly reduced for TT carriers, while patients possessing at least one C allele at the rs794185 exhibited a reduced likelihood of experiencing severe COVID-19." (PMID 38540990, 2024). "This suggests that the association between SUMF1 and COVID-19 severity may be due to the following two factors." (PMID 37344788, 2023). "So, systemic multi-system dysfunction caused by SUMF1 gene mutations may also promote the occurrence of severe COVID-19." (PMID 37344788, 2023). "However, to some extent, it can reflect the relationship between SUMF1 gene and the severity of COVID-19." (PMID 37344788, 2023). "So far, there are no studies showing the relationship between SUMF1 gene and COVID-19 severity." (PMID 37344788, 2023). "However, there are no studies showing a relationship between SUMF1 gene and COVID-19." (PMID 37344788, 2023).
glioblastoma (2 papers, 2023 to 2024). The most malignant astrocytic tumor (WHO grade IV). "SUMF1 was downregulated in oligoastrocytoma and oligodendroglioma tissues and overexpressed in glioblastoma tissues relative to astrocytoma tissues." (PMID 38460946, 2024). "Oligodendroglioma and glioblastoma tissues exhibited more SUMF1 than did oligoastrocytoma tissues." (PMID 38460946, 2024). "Glioblastoma tissues exhibited a higher expression of SUMF1 than did oligodendroglioma tissues." (PMID 38460946, 2024).
leukodystrophy (2 papers, 2021 to 2022). Leukodystrophies are a group of rare, progressive, metabolic, genetic diseases that affect the brain, spinal cord and often the peripheral nerves. "The MRI changes of leukodystrophy has been described as typical finding for patients with this SUMF1 variant." (PMID 35663206, 2022).
psychosis (2 papers, 2022 to 2025). "For example, we have recently identified that genetic variation in SUMF1, which encodes the formylglycine generating enzyme protein, SUMF1, is associated with psychosis risk in AD in a genome-wide analysis." (PMID 35309563, 2022). "Additionally, GWASs have identified loci associated with psychosis in AD, including ENPP6 and SUMF1." (PMID 40004081, 2025).
retinitis pigmentosa (2 papers, 2020 to 2024). Retinitis pigmentosa (RP) is an inherited retinal dystrophy leading to progressive loss of the photoreceptors and retinal pigment epithelium and resulting in blindness usually after several decades. "This individual with non-syndromic retinitis pigmentosa therefore represents the mildest SUMF1-associated phenotype to date." (PMID 38863195, 2024).
schizophrenia (2 papers, 2017). A major psychotic disorder characterized by abnormalities in the perception or expression of reality. "Examples include SUMF1, KDM5B and MXRA5 (Known-ASD genes), PRODH2 and KCTD21 (implicated in schizophrenia), as well as USP9X and SMS (implicated in intellectual disability)." (PMID 28720891, 2017). "We also identified a novel 280-kb deletion at 3p26.1 overlapping genes SUMF1 and ITPR1 in a participant with schizophrenia-NVLD that has not been previously reported in the literature." (PMID 29187259, 2017). "We also identified a novel 280 kb deletion at 3p26.1 overlapping schizophrenia candidate genes ITPR1 and SUMF1 that has not been previously reported in the literature." (PMID 29187259, 2017).
autoimmune disease (1 paper, 2023). A disorder resulting from loss of function or tissue destruction of an organ or multiple organs, arising from humoral or cellular immune responses of the individual to their own tissue constituents. "SUMF1 gene polymorphism rs794185, as a genetic factor significantly related to autoimmune disease MS, has been confirmed by GWAS." (PMID 37344788, 2023).
blood disease (1 paper, 2021). A disease that occurs in the blood. "The top candidates include TNFAIP3, which has been reported before, but also include other, novel regions, containing genes involved in blood diseases (CYCS), neurological diseases (PRKCH, KCNH5, LRNN1), metabolism (SFRP4, SUMF1), and skin development (ASCL4, RAB27A)." (PMID 34032215, 2021).
cerebellar ataxia (1 paper, 2025). A neurological syndrome characterized by clumsy and uncoordinated movement of the limbs, trunk, and cranial muscles. "in an Australian family with pure cerebellar ataxia with deletions of exons 1–10 of ITPR1 and half of the SUMF1 gene." (PMID 41325768, 2025).
cortical blindness (1 paper, 2022). "Our patient had severe seizures that were difficult to control and was later diagnosed with cortical blindness, none of which have been previously attributed to this SUMF1 variant." (PMID 35663206, 2022).
gout (1 paper, 2024). A condition characterized by painful swelling of the joints, which is caused by deposition of urate crystals. "SMR analysis (P < 0.05) at the protein level added emphasis on the impact of the risk genes NRBP1 and SUMF1 on gout." (PMID 39734218, 2024). "Ultimately, eight genes were identified as possible drug targets in gout, including three risk genes (ALDH3B1, NRBP1, SUMF1) and three protective genes (FCGR2B, RCE1, SLC7A7)." (PMID 39734218, 2024). "At the protein level, SMR analysis revealed significant causal associations between IL2RB, NRBP1, SUMF1, and THBS3 levels and the risk of gout." (PMID 39734218, 2024). "However, only NRBP1 and SUMF1 were consistent with the direction of the effect of gout-producing SMR estimates at the protein and transcriptome levels." (PMID 39734218, 2024). "SMR analysis of DNA methylation levels and gout causal gene expression identified seven DNA methylation sites (ALDH3B1: cg18412889, cg23121335, cg25402137; IL2RB: cg25246692, cg11558856; NRBP1: cg15478930; SUMF1: (cg24840601) modifications may regulate ALDH3B1, IL2RB, NRBP1 and SUMF1 expression." (PMID 39734218, 2024). "Eight potential therapeutic targets (ALDH3B1, FCGR2B, IL2RB, NRBP1, RCE1, SLC7A7, SUMF1, THBS3) for gout were identified in the discovery cohort using MR analysis." (PMID 39734218, 2024). "This study identified eight potential drug-targeting genes for gout, among which NRBP1 and SUMF1 have a greater potential for development." (PMID 39734218, 2024).
Hydrocephalus (1 paper, 2016). Hydrocephalus is an active distension of the ventricular system of the brain resulting from inadequate passage of CSF from its point of production within the cerebral ventricles to its point of absorption into the systemic circulation. "Two genes located in the common segmental duplication of four patients, SUMF1 mutations result in defective post-translational modification of sulfatases, and show association with mental retardation, neurological deterioration, hydrocephalus and so on." (PMID 27099631, 2016).
hydrops fetalis (1 paper, 2024). Hydrops fetalis is a severe and challenging fetal condition usually defined as the excessive accumulation of fetal fluid within the fetal extravascular compartments and body cavities that manifests as edema, pleural and pericardial effusion and ascites. "It is therefore believed that MSD is largely caused by hypomorphic SUMF1 variants; indeed, biallelic loss of function alleles in SUMF1 have only very rarely been reported in cases of hydrops fetalis, and appear incompatible with life." (PMID 38863195, 2024).
Hypertension (1 paper, 2016). The presence of chronic increased pressure in the systemic arterial system. "Notably, SUMF1, F2R and IQGAP2 (found in the case group) and ACSF3 (found in the control group) identified in the initial study were replicated in the replication cohort, suggesting potential role of these genes in pathophysiology of hypertension related LVH." (PMID 26930585, 2016).
Mucopolysaccharidosis Type IIIA (1 paper, 2023). "Another article described the safety and efficacy of intracerebral injection of an AAV encoding genes N-sulfoglycosamine sulfohydrolase (SGSH) and sulfatase-modifying factor (SUMF1) in four children with Mucopolysaccharidosis Type IIIA (MPS Type IIIA) disease." (PMID 37240368, 2023).
Retinal dystrophy (1 paper, 2024). Retinal dystrophy is an abnormality of the retina associated with a hereditary process. "This study describes three individuals with an attenuated systemic phenotype, including non-syndromic retinal dystrophy, due to biallelic variants in SUMF1." (PMID 38863195, 2024). "We present clinical and molecular characterisation of three unrelated patients aged 13 to 58 years with milder clinical manifestations due to SUMF1 disease variants, including two adult patients presenting with apparent non-syndromic retinal dystrophy." (PMID 38863195, 2024). "These cases are suggestive that non-null SUMF1 genotypes can cause an attenuated clinical phenotype, including retinal dystrophy without systemic complications, in adulthood." (PMID 38863195, 2024). "These cases reveal the existence of attenuated forms of MSD, expanding the phenotypic spectrum associated with SUMF1 variants, and highlighting a novel association with non-syndromic retinal dystrophy." (PMID 38863195, 2024).
cancer (4 papers, 2019 to 2025). A tumor composed of atypical neoplastic, often pleomorphic cells that invade other tissues. "Specifically, the overexpression of SUMF1 emerged as an independent risk factor for cancer progression." (PMID 38460946, 2024). "In the present study, we validated six direct targets of EZH2 that are GPNMB, PMEPA1, CoL5A1, VGLL4, POMT2 and SUMF1 associated with cancer related pathways." (PMID 30760814, 2019). "Inhibiting the expression of SUMF1 was observed to deter the proliferation, migration, and invasion of cancer cells." (PMID 38460946, 2024). "The heightened expression of SUMF1 was also significantly correlated with cancer diagnosis, IDH status, age, histological subtype, and prognosis." (PMID 38460946, 2024). "We found that the expression of SUMF1 and SUMF2 was upregulated in 8 and 10 different cancer types, respectively." (PMID 39915362, 2025).
tumor (2 papers, 2019 to 2023). "GPNMB and CoL5A1 are the reported oncogenes; PMEPA1, POMT2, VGLL4 and SUMF1 show better survival and thus suggest tumor suppressive role are being regulated by EZH2 signifying its dual role." (PMID 30760814, 2019). "Corroborating the survival curve data, SUMF1 expression in more aggressive ER negative breast cells and higher-grade tumor was found to be abrogated." (PMID 30760814, 2019).
skeletal dysplasia (1 paper, 2009). Any Mendelian diseases that affects growth and development of the skeleton. "The present data also provides an indication of a putative defect in GAG sulfation, which may lead to dramatic biological effects, as exemplified by mutations in PAPSS2, SLC26A2, gPAPP or SUMF1, all causing skeletal dysplasias." (PMID 19898608, 2009).
SUMF1 also shares sentences with these, for which no sentence is quoted: mucopolysaccharidoses (3 papers); developmental delay (2); metabolic disorder (2); astrocytoma (1); autosomal dominant cerebellar ataxia (1); Brain atrophy (1); breast tumors (1); epilepsy (1); genetic disorder (1); globoid cell leukodystrophy (1); ichthyosis (1); infection (1); Intellectual disability (1); Lipid storage disease (1); Maroteaux-Lamy disease (1); Menkes disease (1); metachromatic leukodystrophy (1); neurodegenerative disease (1); neurological diseases (1); oligoastrocytoma (1); oligodendroglioma (1); peripheral neuropathy (1); tuberculosis (1).